SERPINA1 (serpin family A member 1)
Diseases named in the same sentence as SERPINA1 in open-access papers (continued):
Sharing a sentence is not in itself a finding about the gene and the disease.
salivary gland tumors (1 paper, 2024). "Some of the identified peptides were derived from proteins previously suggested as potential biomarkers of salivary gland tumors (ANXA1, BPIFA2, FGB, GAPDH, HSPB1, IGHG1, VIM) or tumors of other tissues or organs (SERPINA1, APOA2, CSTB, GSTP1, S100A8, S100A9, TPI1)." (PMID 39201484, 2024).
skin cancer (1 paper, 2021). "Previous studies have shown that the expression of SERPINA1 is associated with poor prognosis in patients with lung, colon, and skin cancer." (PMID 34692659, 2021).
substance abuse (1 paper, 2022). The use of a drug for a reason other than which it was intended or in a manner or in quantities other than directed. "This peak includes candidate genes, such as SERPINA1 and SERPINA2 (serine-peptidase inhibitor, clade A, members 1 and 2), which were previously implicated in a GWAS for substance abuse vulnerability." (PMID 35629112, 2022).
thyroid nodule (1 paper, 2011). A small circumscribed mass in the THYROID GLAND that can be of neoplastic growth or non-neoplastic abnormality. "To validate these findings and to quantify the discriminatory power of SERPINA1 for the detection of PTC, we performed RT-qPCR experiments on an independent set of thyroid nodules (instantaneous sections) measuring the mRNA levels of SERPINA1." (PMID 21470421, 2011).
tumor (141 papers, 1987 to 2026). "These pathway-level changes were accompanied by reduced expression of transcripts frequently associated with tumor-promoting programs, such as SERPINA1, MDM2, PDGFA, TGFBR1/2, and SPINK1." (PMID 41596590, 2026). "Several studies have demonstrated a close association between SERPINA1 and digestive tract tumors, indicating a strong correlation with tumor-infiltrating lymphocytes." (PMID 39493752, 2024). "In clinical studies, increased expression of SerpinA1 in tumor tissues was associated with larger tumor size, metastasis and poor survival in colorectal and gastric cancer patients." (PMID 38279150, 2024). "SERPINA1 (alpha1AT) expression was also significantly associated with radiation carcinogenesis (I-131 exposure) in tumor tissues from post-Chernobyl PTC cases." (PMID 35295987, 2022). "AAT, encoded by SERPINA1 in humans, is a serine protease inhibitor that influences tumor behavior depending on the context and/or cancer type." (PMID 32224886, 2020). "Regarding the prognostic value of SERPINA1, higher expression of this gene in tumor tissue, especially in current smokers, was associated with better overall and disease-free survival." (PMID 31487965, 2019). "In the current study, we investigated whether protein expression of REG4, SPINK4 and alpha-1 antitrypsin (A1AT, encoded by SERPINA1) in the tumor associated with CAT in an independent cohort of CRC patients." (PMID 38066386, 2024). "We found genes SERPINA1 and risk score were significantly related to tumor stage, T, M, and N." (PMID 34315829, 2021). "In addition, SERPINA1 modulates activity and invasiveness of tumor cells, which is associated with lymph node metastasis and poor prognosis." (PMID 33397428, 2021). "SERPINA1, functioning as a serine protease inhibitor, is known to exhibit robust links to tumor invasion, metastasis, as well as proliferation." (PMID 41252877, 2025). "For example, SERPINA1, a gene that regulates inflammation, ECM remodelling and cell signalling, has been reported to be associated with tumour cell proliferation." (PMID 40847563, 2025). "Nevertheless, our data provide compelling evidence that SERPINA1 upregulation represents a cell-autonomous adaptive survival mechanism, enabling tumor cells to withstand therapeutic stress and enhance their metastatic competence." (PMID 41467954, 2025). "Conversely, genetic ablation of SERPINA1 expression markedly suppressed tumor progression, resulting in significantly reduced tumor volumes relative to control (P < 0.05)." (PMID 41467954, 2025). "Under hypoxic and chemotherapeutic challenge, SERPINA1 overexpression significantly promoted tumor growth, yielding larger tumor volumes and sizes compared to control (P < 0.05)." (PMID 41467954, 2025). "While SERPINA1, a serine protease inhibitor involved in tumor microenvironment regulation, is dysregulated in various cancers, its role in TACE resistance is unclear." (PMID 41467954, 2025). "SERPINA1 plays a key role in the communication between endothelial and tumor cells within the TME, impacting various aspects of cancer development and progression." (PMID 39851516, 2025). "In the group “Alive or Dead Tumor Free”, the median SERPINA1 expression was 10.50, in contrast to the “Dead With Tumor” group, which showed a significantly lower median of 9.53." (PMID 39851465, 2024). "Specifically, tumor tissues show increased expression of SERPINA1, RASGRP1, and CFB compared to normal tissues, whereas C1S, SERPINF2, and TLN2 display the opposite pattern." (PMID 38751445, 2024). "Transwell migration and Transwell invasion experiments indicated that less tumor cells traversed the chambers in the SERPINA1 Knockdown group." (PMID 38710698, 2024). "Only one report has demonstrated the potential effect of CVD through SerpinA1 on the enhancement of tumor growth." (PMID 38279150, 2024). "It has been demonstrated that SerpinA1 promotes growth in various types of tumor, however, the evidence in CVD models is still very limited." (PMID 38279150, 2024).
tumor (continued). "In an MI-induced HF mouse model in which enhanced tumor growth was found, increased cardiac SerpinA1 expression was demonstrated." (PMID 38279150, 2024). "In summary, our findings suggest that SERPINA1 is highly expressed in CRC and associated with tumor progression." (PMID 38710698, 2024). "For example, SERPINA1 expression was significantly connected to adjacent inflammation, tumor size, pathologic stage, and AFP level in LIHC." (PMID 37511325, 2023). "In this study, we first explored the differential expressions of SERPINA1 in tumor and normal tissues through multiple databases." (PMID 37511325, 2023). "Compared with OBs, CSC-like cells overexpressed SPP1 and SERPINA1 genes related to tumor progression." (PMID 36588108, 2023). "The study was designed to elucidate the potential of SERPINA1 in tumor prognosis and immunotherapy, thus providing novel insight into the antitumor strategy." (PMID 37511325, 2023). "Similar observations were made in an important study published in 2019 at the German Agency for Lung Research, in which tumor and surrounding non-tumor tissues from the lung of 351 NSCLC patients were analyzed for SERPINA1 expression." (PMID 37501182, 2023). "For example, SERPINA1 showed close connections to CD8A in CD8+ T cells, CD68 in tumor-associated macrophages, IRF6 in M1 macrophages, NRP1 in DCs, STAT3 and IL17A in Th17 in most digestive cancers." (PMID 37511325, 2023). "We also analyzed the potential connection between SERPINA1 level and immune and molecular subtypes, biomarkers of therapeutic efficacy, and tumor-infiltrating lymphocytes." (PMID 37511325, 2023). "SERPINA1 promotes a better prognosis of PTC-W possibly through tumour inhibition signalling pathways, such as the KRAS and NF-kB signalling pathways." (PMID 37455914, 2023). "There was a strong connection between SERPINA1 expression and tumor-infiltrating lymphocytes, and SERPINA1 showed significant relation to gene markers of immune cells in digestive tumors." (PMID 37511325, 2023). "We then explored the relationship between tumor antigens (CCNE1, PLK1, and SERPINA1) and ICD risk score using Pearson correlation analysis." (PMID 36393842, 2022). "SERPINA1, a plasma protein, is synthesized mainly in hepatocytes, which is mainly involved in angiogenesis, intravascular fibrinolysis, wound healing, tumor invasion, and metastasis." (PMID 34621293, 2021). "SERPINA1 is synthesized and released by tumor cells and plays major roles in physiologic and pathologic processes such as angiogenesis, tumor invasion and metastasis." (PMID 33182810, 2020). "Data from lung tissue analysis clearly show that the expression levels of SERPINA1 are highly variable but significantly lower in tumor tissue compared to adjacent normal lung tissue." (PMID 31487965, 2019). "On the other hand, systemic inflammation, which assists tumor grow, is related to the activation of IL-6 and IL-1β pathways which are responsible for induction of SERPINA1 expression." (PMID 31487965, 2019). "In general, SERPINA1 expression was significantly lower in tumor tissues than in adjacent normal lung tissue." (PMID 31487965, 2019). "Lower SERPINA1 expression in tumor but higher in adjacent non-tumor lung tissues (n = 351, p = 0.016) as well as higher serum levels of AAT protein (n = 170, p = 0.033) were associated with worse survival rates." (PMID 31487965, 2019). "Specifically, in current smokers a higher tumor expression of SERPINA1 was significantly related to the better overall survival as well as disease-free survival." (PMID 31487965, 2019). "If SERPINA1 expression and AAT levels relate to hypoxia during tumor development in vivo, warrants further studies." (PMID 31487965, 2019). "Based on the Cox regression univariate analysis we found that higher SERPINA1 expression in adjacent non-tumor tissue is related to worse overall survival." (PMID 31487965, 2019).
tumor (continued). "Taken together, the relation of SERPINA1 gene expression, AAT tumor levels and patients’ serum concentrations in the situation of an acute NSCLC is very complex." (PMID 31487965, 2019). "The histological classification of CTVT was mainly based on positive immunostaining for lysozyme (encoded by LYZ), α1-antitrypsin (encoded by SERPINA1), and vimentin (encoded by VIM) in about 30%–50% of the tumor cells." (PMID 29634949, 2018). "Conversely, SERPINA1 knockdown elicited opposing trends, indicating that SERPINA1 may promote tumor progression by modulating ITGB3." (PMID 41467954, 2025). "SERPINA1, a 1-antitrypsin primarily synthesized in specific cells, plays multiple roles in physiological and pathological processes such as angiogenesis, intravascular fibrinolysis, and tumor metastasis." (PMID 40520228, 2025). "Notably, SERPINA1 overexpression markedly enhanced tumor growth while concurrently increasing ITGB3 expression." (PMID 41467954, 2025). "Given the established link between inflammation and cancer progression, elevated SERPINA1 levels may therefore promote tumor resistance and aggressiveness through such specific mechanisms." (PMID 41467954, 2025). "Thus, SERPINA1 is integral to the crosstalk between endothelial cells and neoplasms, influencing myriad facets of cancer pathogenesis and evolution." (PMID 39851516, 2025). "Mechanistically, we revealed that SERPINA1 might mediate CEBPB-induced promotion of tumor cell growth and migration via STAT3 signaling for the first time." (PMID 38710698, 2024). "SERPINA1, MAP1LC3A, DIRAS3 were down-regulated in a high risk group and up-regulated in a low risk group, which were potentially tumor suppressor genes; HSPA8, HSPB8 were up-regulated in a high risk group and down-regulated in a low risk group, which were probably promoting oncogenes." (PMID 34876005, 2021). "Second, cancer cells and cancer-associated cells express SERPINA1 gene themselves and can also uptake exogenous AAT, which may help to develop a favorable microenvironment for the tumor progression." (PMID 31487965, 2019). "However, further investigations on the mechanisms behind the regulation of SERPINA1 expression and AAT protein production in tumor cells are needed to complete our understanding on the role of AAT in NSCLC." (PMID 31487965, 2019). "SerpinA1 overexpression was correlated with mean tumor size (P = 0.014)." (PMID 26015410, 2015). "SerpinA1 has been reported to regulate the aggregation of fibronectin on surfaces of tumor cells, which may increase the probability of metastasis." (PMID 26015410, 2015). "For serpinA1, cytoplasmic staining in tumor cells was considered positive." (PMID 26015410, 2015). "Together these studies and our findings suggest that Igfbp1 and Serpina1 may play critical roles in tumor progression in vivo, and are potential candidates for therapeutic interventions." (PMID 18218118, 2008). "However, clinical studies have shown that high circulating levels of Serpina1 directly correlate with tumor progression." (PMID 18218118, 2008). "Particularly, SERPINA1, a serine protease inhibitor that belongs to the protease inhibitor family, is synthesized and released by tumor cells and is involved in a variety of physiological and pathologic processes including angiogenesis, tumor invasion, and metastasis." (PMID 35205837, 2022). "The high expression of SERPINA1 may protect tumor cells from enzymes and immune system." (PMID 36349191, 2022). "However, there was little difference in SERPINA1 staining levels between normal and tumor tissues." (PMID 34315829, 2021). "In addition, the three-gene risk-score model (involving MFI2, FOXM1, and GPC3) for LUAD and the two-gene risk-score model (involving SERPINA1 and FOXM1) for LUSC might be useful in predicting the prognosis of tumour patients." (PMID 34112123, 2021). "However higher SERPINA1 expression within a tumor tissue is related to better patient`s prognosis." (PMID 31487965, 2019).
tumor (continued). "IHC staining revealed a significant downregulation of SERPINA1 in tumor tissues from HIV-positive patients (Figure 6A1, A2) compared to their adjacent non-tumor tissues (Figure 6A3, A4)." (PMID 41584047, 2026). "Through integrated clinical and mechanistic investigations, we demonstrate that SERPINA1 promotes TACE resistance in HCC by maintaining elevated serum levels post-treatment and driving tumor aggressiveness under therapeutic stress." (PMID 41467954, 2025). "It demonstrated a notably elevated expression of SERPINA1, RASGRP1, and CFB in tumor tissues, while C1S and TLN2 showed significantly higher expression in normal tissues." (PMID 38751445, 2024). "Compared with normal samples, the expressions of HSPA1A, HSPB1 and SERPINA1 were down-regulated in tumor samples, while TIMP1 was up-regulated in tumor samples." (PMID 39115879, 2024). "Focusing on the reduced MGAT1 expression in tumor regions, we analyzed the interaction between MGAT1-Macrophages and monocytes, mediated by the SERPINA1_LRP1 ligand-receptor pair." (PMID 39081317, 2024). "SERPINA1, ITLN1, and REG4 upregulation in primary tumor tissues was negatively correlated with distant metastasis, indicating a protective effect on prognosis in patients with CRC." (PMID 38083905, 2023). "Of note, seventeen of thirty-nine proteins are reported as urine biomarkers in different diseases, of which eight proteins (PEBP1, EPS8L2, SERPINA1, FGA, SPINT1, CD55, SPARC, and GINM1) are related to neoplastic disease in urine specimens." (PMID 36918772, 2023). "On the other hand, the results showed that, for LUSC tumor samples, CDH2, SPP1, and TNC were significantly upregulated and FN1, CYR61, SERPINA1, and IL6 were significantly downregulated compared to their respective controls." (PMID 37887075, 2023). "SERPINA1 promotes a better prognosis for PTC-W, possibly through a tumour inhibition signalling pathway." (PMID 37455914, 2023). "As a result, we assume that the PTC-W group exhibiting SERPINA1 expression has a better prognosis than the PTC-WO group exhibiting SERPINA1 expression, possibly because it involved tumour inhibition signalling pathways." (PMID 37455914, 2023). "To determine the immune value of SERPINA1 in the tumor microenvironment (TME), we explored the connections between SERPINA1 expression and TMB and MSI, which have been confirmed to influence immunotherapy efficacy significantly." (PMID 37511325, 2023). "The serpin family A member 1 (SERPINA1) gene is upregulated and is a marker of poor prognosis for several cancers which was also significantly downregulated in tumor cells following ADMC challenge (1.4 fold)." (PMID 35574362, 2022). "IFI27, LCN2, GAST, and SERPINA1 were downregulated after NACT in tumor cells, while OLFM4, MRPS35, MMP1 and MED21 were upregulated in tumor cells." (PMID 36474268, 2022). "IHC staining of tumor sections from PDAC patients showed that MUC5B and SERPINA1 are expressed by PDAC stromal cells (as well as by cancer cells)." (PMID 36316305, 2022). "Serpin peptidase inhibitor clade A member 1 (SERPINA1), a protease inhibitor, is essential for biological processes, including angiogenesis, immunoreaction, tumor invasion, and metastasis." (PMID 34707986, 2021). "We identified an increased expression of genes that were previously found in the astrocytes from tumor specimens, (HLA-DRA, CHI3L1 SERPINA1, CCL18, CD37, and CD274)." (PMID 31186414, 2019). "Osteopontin (OPN; SPP1) and two proteins of the serpin family, such as SERPINA1 and SERPINA3, were those with higher expression in the P3 subtype compared to the rest of tumours." (PMID 31560832, 2019). "Tumor and adjacent non-tumor lung tissues and serum samples from 351 NSCLC patients were analyzed for SERPINA1 expression and AAT protein levels." (PMID 31487965, 2019).